NKAP (NFKB activating protein)
Description:
Acts as a transcriptional repressor. Plays a role as a transcriptional corepressor of the Notch-mediated signaling required for T-cell development. Also involved in the TNF and IL-1 induced NF-kappa-B activation. Associates with chromatin at the Notch-regulated SKP2 promoter.
Synonyms: FLJ22626; MRXSHD
Tractability: Small molecule: a structure with a bound ligand is known. PROTAC: UniProt records ubiquitination sites on it; ubiquitination databases record sites on it; its protein half-life has been measured.
Gene: Protein-coding gene on chromosome X (119,920,672 to 119,943,751, reverse strand). Ensembl gene ENSG00000101882.
Subcellular location: Nucleus
Subcellular location (Human Protein Atlas): Nucleoplasm; Cytosol
Pathways (Reactome):
Metabolism of RNA: mRNA Splicing - Major Pathway
Gene Ontology:
Molecular function: chromatin binding; protein binding; RNA binding; chromatin DNA binding
Biological process: negative regulation of DNA-templated transcription; negative regulation of transcription by RNA polymerase II; positive regulation of alpha-beta T cell differentiation; mRNA splicing, via spliceosome
Cellular component: nucleoplasm; nucleus; spliceosomal complex; U2-type catalytic step 2 spliceosome
Homologues: Orthologues: chimpanzee NKAP (99% identical), macaque NKAP (99% identical), dog NKAP (94% identical), rabbit NKAP (94% identical), pig NKAP (93% identical), rat Nkap (91% identical), mouse Nkap (90% identical). Paralogues in human: NKAPL (63% identical).
Diseases named in the same sentence as NKAP in open-access papers:
NKAP is named in the same sentence as 26 diseases in open-access papers, as found by Europe PMC text mining. Sharing a sentence is not in itself a finding about the gene and the disease. The quoted sentences say what the papers report.
glioblastoma (6 papers, 2022 to 2025). The most malignant astrocytic tumor (WHO grade IV). "NKAP expression was associated with the sensitivity of glioblastoma cells to the ferroptosis inducers erastin, iFSP1, and SAS." (PMID 35064112, 2022). "However, it remained unclear why NKAP deletion caused glioblastoma cell death." (PMID 35064112, 2022). "NKAP acts as a novel ferroptosis inhibitor and the downregulation of NKAP directly induces ferroptosis in glioblastoma cells." (PMID 38785921, 2024). "Transcriptome profiling was performed using the TCGA clinical glioblastoma database (Public data, Project ID: TCGA-GBM, 166 glioblastoma cases) to investigate the correlation between NKAP and SLC7A11." (PMID 35064112, 2022). "We identified NKAP as a new ferroptosis suppressor, and the knockdown of NKAP directly led to ferroptosis in glioblastoma cells." (PMID 35064112, 2022). "In summary, we found that glioblastoma cells with NKAP knockdown had a higher lipid peroxidation level and typical ferroptosis characteristics." (PMID 35064112, 2022). "In the present study, we first identified the subtle relationship between NKAP, ferroptosis, and m6A modification in glioblastoma cells." (PMID 35064112, 2022). "In the present study, we demonstrated that NKAP knockdown induced ferroptosis in glioblastoma cell lines U87MG and U251." (PMID 35064112, 2022). "NKAP protected glioblastoma cells from ferroptosis by positively regulating SLC7A11 expression." (PMID 35064112, 2022). "An interesting aspect that attracted us most was that NKAP knockdown induced increased lipid peroxidation in naive T cells and a higher death rate in colon cancer cells; these findings were similar to some of our research results on glioblastoma." (PMID 35064112, 2022). "Here, we found NKAP knockdown induced cell death in glioblastoma cells." (PMID 35064112, 2022). "We constructed a lentivirus-mediated RNAi targeting NKAP (shNKAP) and a lentiviral vector carrying the NKAP gene (Lv-NKAP) by transfecting to two human glioblastoma cell lines U87MG and U251, and then tested their interference effect and overexpression level by western blot." (PMID 35064112, 2022). "NKAP knockdown combined with ferroptosis induction therapy may be an effective treatment for glioblastoma in the future." (PMID 35064112, 2022). "NKAP protects glioblastoma (GBM) cells from ferroptosis by upregulating SLC7A11 and promoting cell resistance to ferroptosis inducers." (PMID 37375731, 2023). "However, there was no literature reported the relationship between NKAP and ferroptosis in glioblastoma cells." (PMID 35064112, 2022). "However, there is no literature reporting the relationship between NKAP and ferroptosis in glioblastoma cells and the mechanism of NKAP modulating ferroptosis." (PMID 35064112, 2022).
breast carcinoma (4 papers, 2019 to 2022). "miR-4766-5p impeded the developing process of tumors by regulating different targets, including SIRT1 in breast cancer and NKAP in GC." (PMID 34616917, 2021). "In hepatocellular carcinoma and breast cancer, NKAP promotes the proliferation and invasion of tumor cells through the AKT/mammalian target of the rapamycin signaling pathway." (PMID 33553160, 2020). "In addition, NKAP is up-regulated in many kinds of tumors, such as colon cancer, hepatocellular carcinoma, breast cancer, and so on." (PMID 35005769, 2022). "In addition, NKAP functions as an oncogene in breast cancer, hepatocellular carcinoma, and renal cell carcinoma through the protein kinase B/mammalian target of the rapamycin signaling pathway." (PMID 33553160, 2020).
glioma (4 papers, 2019 to 2022). A benign or malignant brain and spinal cord tumor that arises from glial cells (astrocytes, oligodendrocytes, ependymal cells). "Cell viability of U87MG and U251 glioma cell lines, when grown in the indicated concentration of erastin for 24 h, was significantly lower in the shNKAP group and higher in the Lv-NKAP group." (PMID 35064112, 2022). "In glioma, NKAP can accelerate gliomas via Notch1 signaling and is considered an important oncogenic factor." (PMID 33553160, 2020). "Although NKAP inhibited the Notch1 downstream pathway in the immune system, our study revealed that it activated the Notch signaling in gliomas." (PMID 31277684, 2019). "More importantly, we detected that cellular proliferation, migration and invasion were significantly inhibited upon NKAP knockdown in the cell lines of gliomas." (PMID 31277684, 2019). "By use of tissue collection and immunohistochemical analysis, we observed that the expression of NKAP was significantly upregulated in the gliomas." (PMID 31277684, 2019). "Overall, our findings provided new insight into the regulatory relationship between NKAP and Notch1 in the tumorigenesis of gliomas." (PMID 31277684, 2019). "NKAP silencing significantly inhibited the proliferation, migration and invasion of glioma cells, whereas overexpression of NKAP induced aggressive cellular behavior." (PMID 31277684, 2019). "In this study, we provided the first evidence showing the functional roles of NKAP in gliomas by targeting Notch1 signaling." (PMID 31277684, 2019). "What’s more, we provided unequivocal evidence for the first time demonstrating that NKAP performed its function in part via regulating glioma immune microenvironment through targeting Notch1." (PMID 31277684, 2019). "Collectively, these data suggested that NKAP was indeed involved in the proliferative ability of gliomas by inducing G1/S arrest, especially in U87 cells." (PMID 31277684, 2019). "In summary, we have identified NKAP as an important oncogenic factor in gliomas, and indicated its ability to promote glioma proliferation and invasion." (PMID 31277684, 2019). "The level of increase in NKAP expression was positively correlated with the degree of glioma malignancy and inversely correlated with the prognosis." (PMID 31277684, 2019). "Consistently, the mRNA and protein levels of SDF-1 were also down-regulated in the NKAP depleted glioma cells." (PMID 31277684, 2019). "Taken together, these results evidently suggested that NKAP together with Notch1 signaling was involved in regulation of the immune microenvironment of gliomas." (PMID 31277684, 2019). "Collectively, these results evidently suggested that NKAP was involved in the recruitment and polarization of TAMs in gliomas." (PMID 31277684, 2019). "To elucidate the functions of NKAP in gliomas, we firstly tested the effects of NKAP on glioma cell growth." (PMID 31277684, 2019). "To further identify the potential NKAP targets in gliomas, we performed RNA sequencing in triplicates to determine the gene expression profiles of the control and NKAP knockdown cell lines." (PMID 31277684, 2019). "The results showed that proportion of CD206high macrophages was much less in the gliomas knockdown with NKAP in comparison to scrambled controls." (PMID 31277684, 2019). "Immunoblotting also confirmed this phenomenon, evidently suggesting the important role of NKAP in glioma cell migration and invasion." (PMID 31277684, 2019). "When we looked at the tumor-stromal boundary in the xenografted mice, a decrease in SDF-1 expression was observed in the glioma tissues knockdown of NKAP." (PMID 31277684, 2019). "Taken together, it is concluded that NKAP performs its oncogenic functions via Notch1 signaling, and this finding provides a novel perspective to find potential therapeutic targets for gliomas." (PMID 31277684, 2019).
glioma (continued). "We additionally detected the cytokines released by the co-cultured glioma cells, and found that NKAP positively controlled M-CSF secretion." (PMID 31277684, 2019). "The expression of NKAP and Notch1 in glioma and normal human brain samples were analyzed by immunohistochemical analysis." (PMID 31277684, 2019). "In 2019, we reported that NKAP alters tumor immune microenvironment and promotes glioma growth." (PMID 35064112, 2022). "Downregulation of NKAP in gliomas had abrogated tumor growth and invasion in vitro and in vivo." (PMID 31277684, 2019). "NKAP (NF-κB activating protein) is a widely expressed 415-amino acid nuclear protein that is overexpressed by gliomas, but its function in glioma was still unknown." (PMID 31277684, 2019). "Given that NKAP promotes glioma cell proliferation and invasion and that Notch1 is a potential target of NKAP, we next investigated whether Notch1 represented a functional link for the biological changes observed in the glioma cells with NKAP deletion." (PMID 31277684, 2019). "In addition, cell cycle flow cytometry showed that depletion of NKAP resulted in a marked inhibition of the S phase among glioma cells." (PMID 31277684, 2019). "To verify whether NKAP participated in EMT of glioma cells, we detected the mRNA levels of several representative EMT markers." (PMID 31277684, 2019). "In contrast to a higher immunostaining of Notch1 and SDF-1 in the gliomas derived from the cells transduced with scrambled control shRNA, the gliomas depleted of NKAP displayed much lower levels of these two factors, evidently suggesting a regulatory role of NKAP in Notch1 signaling." (PMID 31277684, 2019). "As a corollary, NKAP seemed to be a key regulator of glioma progression and TME, but its molecular mechanisms still remain unclear." (PMID 31277684, 2019). "In this manuscript, we have identified NKAP as an important oncogenic factor in gliomas." (PMID 31277684, 2019). "As such, we speculated that Notch1 might be the potential target of NKAP in the regulation of glioma development and progression." (PMID 31277684, 2019). "Based on our data that NAKP controlled the expression and secretion of SDF-1 and M-CSF via Notch1, it could be concluded NKAP was involved in regulation of the tumor immune microenvironment of gliomas." (PMID 31277684, 2019). "Here we showed that overexpression of NKAP in gliomas could promote tumor growth by contributing to a Notch1-dependent immune-suppressive tumor microenvironment." (PMID 31277684, 2019). "Instead of a repressor component, NKAP transactivated Notch1 in the glioma cells." (PMID 31277684, 2019). "During the five-year follow-up period, the overall survival of the glioma patients with high-level NKAP expression was markedly lower than that of patients with low-level NKAP expression, suggesting that a high level of NKAP was associated with poor prognosis in a long round." (PMID 31277684, 2019). "To further investigate whether NKAP was related to glioma cell migration and invasion, we used a transwell assay to examine the effects of NKAP on U87 and U251 cell movement." (PMID 31277684, 2019). "Most importantly, we found that NKAP could alter the polarization and infiltration of tumor associated macrophages (TAM) via regulating secretion of SDF-1 and M-CSF, indicating that NKAP might contribute to the immune microenvironment of gliomas." (PMID 31277684, 2019). "Considering the in vitro involvement of NKAP in glioma cell proliferation, invasion, migration and EMT, we extended this study to determine the impact of NKAP on tumorigenic capabilities of gliomas in vivo." (PMID 31277684, 2019). "As a corollary, we have demonstrated a model where NKAP positively regulates the expression of Notch1, which results in an increasing secretion of M-CSF of SDF-1 in glioma cells, reinforcing significant bidirectional cross-talks between macrophages and glioma cells." (PMID 31277684, 2019).
glioma (continued). "We infected both U87 and U251 glioma cells with the lentiviruses expressing GFP and siRNA of NKAP." (PMID 31277684, 2019). "As such, we could surmise that NKAP may function in glioma cells via directly binding to the Notch1 promoter." (PMID 31277684, 2019).
scoliosis (3 papers, 2021 to 2026). A congenital or acquired spinal deformity characterized by lateral curvature of the spine. "Deleterious missense mutations in the NKAP gene have been associated with developmental delay, hypotonia, joint contractures, behavioral abnormalities, Marfanoid habitus, and scoliosis." (PMID 37511607, 2023). "Males with NKAP germline missense mutations exhibit developmental delay, hypotonia, joint contractures, behavioral abnormalities, Marfanoid habitus, and scoliosis." (PMID 34445777, 2021).
colon cancer (2 papers, 2022). "Previous studies have reported that knockout of NF-κB activating protein (NKAP), an RNA-binding protein, increased lipid peroxidation level in naive T cells and induced cell death in colon cancer cells." (PMID 35064112, 2022). "NKAP functions as an oncogene and participates in the progression of cancer, including gastric cancer, colon cancer, and renal cell carcinoma." (PMID 35064112, 2022). "Previous studies have reported NKAP knockout increased lipid peroxidation in naive T cells and induced cell death in colon cancer cells." (PMID 35064112, 2022). "NKAP is involved in regulating the growth and invasion of colon cancer cells." (PMID 35005769, 2022).
congenital heart disease (1 paper, 2024). A heart disease that is present at birth. "Here, we elucidate the potential prenatal manifestation of NKAP mutation‐associated disorder for the first time, alongside revealing the relationship between NKAP mutations and congenital heart defect (CHD) in the Chinese population." (PMID 38647244, 2024).
Intellectual disability (1 paper, 2026). "Additionally, the case illustrates the need to test male patients with a Marfanoid phenotype and intellectual disability for mutations in NKAP." (PMID 41917976, 2026).
lung carcinoma (1 paper, 2021). "From a molecular perspective, we propose a novel signaling axis: the MARCKS/NKAP/p65 regulatory axis in smoke-associated lung cancer." (PMID 33754052, 2021). "In all, we have demonstrated marked association between phospho-MARCKS and NF-κB activity in smoke-related lung cancer as well as identified MARCKS as a regulator of NF-κB through NKAP." (PMID 33754052, 2021).
neuroblastoma (1 paper, 2020). Neuroblastoma (NB) is the most common solid, extracranial childhood tumor. "This study aimed to investigate the role of NKAP in neuroblastoma (NB) progression and recurrence." (PMID 33553160, 2020).
soft tissue sarcoma (1 paper, 2016). A malignant neoplasm arising from muscle tissue, adipose tissue, blood vessels, fibrous tissue, or other supportive tissues excluding the bones. "Particularly, NKAP gene deficiency has been observed in soft tissue sarcomas as well as several other types of human cancer." (PMID 27694884, 2016). "Notably, deletion at the NKAP locus was frequently observed in soft tissue sarcomas, with 18.77% (49/261) of tumours exhibiting loss (log2 ratio <−0.3)." (PMID 27694884, 2016). "In addition, loss of NKAP causes chromosome missegregation and aneuploidy and is observed in human soft tissue sarcomas." (PMID 27694884, 2016). "Importantly, loss of NKAP expression causes aneuploidy in cultured cells, and is observed in human soft tissue sarcomas." (PMID 27694884, 2016).
thyroid cancer (1 paper, 2016). "By exploring the GEO database, the significant decrease of NKAP gene expression was found in other two types of human cancers, pancreatic and thyroid cancer." (PMID 27694884, 2016).
tumor (10 papers, 2016 to 2024). "Interestingly, compared to the control group, inhibiting NKAP set up obstacles to tumor-associated macrophage (TAM) polarization and recruitment by decreasing the secretion of SDF-1 and M-CSF." (PMID 31277684, 2019). "In the present study, we show that the Drosophila homologue of NKAP, dNKAP, has a tumor-suppressive activity and prevents genome instability in the wing epithelia." (PMID 38059855, 2024). "In GBM, RNA binding protein NKAP protects tumor cells from ferroptosis by promoting SLC7A11 mRNA splicing in an m6A-dependent manner." (PMID 36266731, 2022). "We established tumor-bearing models of SK-N-SH cells to detect the expression of NKAP protein and verify its function in the PI3K/AKT pathway by Western blotting assay in vivo." (PMID 33553160, 2020). "Since increased expression of stemness related genes are usually pronounced in the malignancy, it has drawn our great attention how NKAP is expressed in the glial-derived tumor cells." (PMID 31277684, 2019). "Knockdown of the Drosophila melanogaster gene CG6066, an NKAP ortholog, led to over proliferation of D. melanogaster neural precursor cells, resulting in lethal tumor formation." (PMID 31277684, 2019). "We observed a decreased tumor volume in the tumor-bearing mice when NKAP was inhibited." (PMID 35064112, 2022). "In addition, YTHDC1, YTHDF1, YTHDF2, IGF2BP3, HNRNPA2B1 and NKAP were confirmed by two databases to be positively correlated with tumor stage, which deserved more attention in the treatment of HCC." (PMID 35963644, 2022). "When the U87 cells transduced with lentiviral vectors expressing NKAP-targeting siRNA or non-targeting control siRNA were subcutaneously implanted into the immunocompromised mice, we observed a significant decrease in tumor formation in the tumor-bearing mice when NKAP was inhibited." (PMID 31277684, 2019). "Despite these advances, in vivo evidence for NKAP/NKAPL driving tumor initiation and progression remains lacking, and the underlying molecular mechanisms are largely unknown." (PMID 38059855, 2024). "Therefore, we investigated the role of NKAP in the tumor proliferation of NB cells in vitro." (PMID 33553160, 2020). "We knocked down NKAP expression in NB1 and SK-N-SH cells by small interfering RNA transfection to verify its role in tumor proliferation, apoptosis, and the phosphatidylinositol 3-kinase/protein kinase B (PI3K/AKT) signaling pathway." (PMID 33553160, 2020).